FBXW11 (F-box and WD repeat domain containing 11)
Description:
Substrate recognition component of a SCF (SKP1-CUL1-F-box protein) E3 ubiquitin-protein ligase complex which mediates the ubiquitination and subsequent proteasomal degradation of target proteins. Probably recognizes and binds to phosphorylated target proteins: the interaction with substrates requires the phosphorylation of the two serine residues in the substrates' destruction motif D-S-G-X(2,3,4)-S. SCF(FBXW11) mediates the ubiquitination of phosphorylated CTNNB1 and participates in Wnt signaling regulation. SCF(FBXW11) plays a key role in NF-kappa-B activation by mediating ubiquitination of phosphorylated NFKBIA, leading to its degradation by the proteasome, thereby allowing the associated NF-kappa-B complex to translocate into the nucleus and to activate transcription. The SCF(FBXW11) complex also regulates NF-kappa-B by mediating ubiquitination of phosphorylated NFKB1: specifically ubiquitinates the p105 form of NFKB1, leading to its degradation. SCF(FBXW11) mediates the ubiquitination of IFNAR1. SCF(FBXW11) mediates the ubiquitination of CEP68; this is required for centriole separation during mitosis. Involved in the oxidative stress-induced a ubiquitin-mediated decrease in RCAN1. Mediates the degradation of CDC25A induced by ionizing radiation in cells progressing through S phase and thus may function in the intra-S-phase checkpoint. Has an essential role in the control of the clock-dependent transcription via degradation of phosphorylated PER1 and phosphorylated PER2. SCF(FBXW11) mediates the ubiquitination of CYTH1, and probably CYTH2. SCF(FBXW11) acts as a regulator of mTORC1 signaling pathway by catalyzing ubiquitination and subsequent proteasomal degradation of phosphorylated DEPTOR, TFE3 and MITF. (Microbial infection) Target of human immunodeficiency virus type 1 (HIV-1) protein VPU to polyubiquitinate and deplete BST2 from cells and antagonize its antiviral action.
Synonyms: HOS; BTRCP2; FBW1B; FBXW1B; KIAA0696; BTRC2; Fbw11; NEDJED
Tractability: Antibody: the Human Protein Atlas places it where antibodies can reach. PROTAC: ubiquitination databases record sites on it; its protein half-life has been measured.
Gene: Protein-coding gene on chromosome 5 (171,861,548 to 172,006,873, reverse strand). Ensembl gene ENSG00000072803.
Subcellular location: Cytoplasm; Nucleus
Subcellular location (Human Protein Atlas): Plasma membrane; Vesicles; Nucleoplasm
Pathways (Reactome):
Immune System: Activation of NF-kappaB in B cells; Antigen processing: Ubiquitination & Proteasome degradation; CLEC7A (Dectin-1) signaling; Dectin-1 mediated noncanonical NF-kB signaling; Downstream TCR signaling; FCERI mediated NF-kB activation; MAP3K8 (TPL2)-dependent MAPK1/3 activation; NIK-->noncanonical NF-kB signaling
Cell Cycle: Regulation of PLK1 Activity at G2/M Transition; Ubiquitin-Mediated Degradation of Phosphorylated Cdc25A
Circadian clock: Degradation of CRY and PER proteins
Metabolism of proteins: Neddylation
Gene Ontology:
Molecular function: protein binding; ubiquitin-like ligase-substrate adaptor activity; ubiquitin protein ligase activity; protein dimerization activity
Biological process: positive regulation of canonical NF-kappaB signal transduction; proteasome-mediated ubiquitin-dependent protein catabolic process; protein polyubiquitination; SCF-dependent proteasomal ubiquitin-dependent protein catabolic process; ubiquitin-dependent protein catabolic process; positive regulation of circadian rhythm; positive regulation of DNA-templated transcription; protein dephosphorylation; protein ubiquitination
Cellular component: centrosome; SCF ubiquitin ligase complex; cytoplasm; cytosol; kinetochore; microtubule cytoskeleton; nucleoplasm; nucleus; ubiquitin ligase complex
Genetic constraint (gnomAD): Loss-of-function variants: 13 observed, 58.35 expected, observed/expected ratio (o/e) 0.22, 90% interval 0.14 to 0.35. The upper end of that interval is the gene's LOEUF score, 0.35, which puts it in group 1 of 6, group 1 being the genes least tolerant of losing a copy. Missense variants: 286 observed, 633.15 expected, observed/expected ratio (o/e) 0.45, 90% interval 0.41 to 0.5. Synonymous variants: 211 observed, 232 expected, observed/expected ratio (o/e) 0.91, 90% interval 0.81 to 1.02.
Homologues: Orthologues: pig FBXW11 (100% identical), rabbit FBXW11 (100% identical), chimpanzee FBXW11 (99% identical), rat Fbxw11 (99% identical), mouse Fbxw11 (99% identical), guinea pig FBXW11 (94% identical), dog FBXW11 (92% identical), zebrafish fbxw11a (86% identical), zebrafish fbxw11b (84% identical), Caenorhabditis elegans lin-23 (56% identical). Paralogues in human: BTRC (83% identical), FBXW7 (22% identical), TRAF7 (17% identical), EFCAB8 (16% identical), FBXW9 (15% identical), WDR49 (15% identical), WDR64 (15% identical), WDR86 (14% identical), FBXW8 (12% identical), PAAF1 (10% identical), WDR54 (9% identical), FBXW12 (9% identical), and 2 more.
Diseases named in the same sentence as FBXW11 in open-access papers:
FBXW11 is named in the same sentence as 39 diseases in open-access papers, as found by Europe PMC text mining. Sharing a sentence is not in itself a finding about the gene and the disease. The quoted sentences say what the papers report.
colorectal cancer (5 papers, 2018 to 2025). A primary or metastatic malignant neoplasm that affects the colon or rectum. "F-box and tryptophan-aspartic (WD) repeat domain containing 11 (FBXW11) modulates the ubiquitination of growth-and invasion-related factors in lung cancer, colorectal cancer, and osteosarcoma." (PMID 40747341, 2025). "Our study aimed to explore the role of FBXW11 in the development and metastasis of colorectal cancer (CRC)." (PMID 34642302, 2021). "For example, FBXW11 plays an important role in controlling the IκB-dependent apoptotic pathway in human melanoma and colorectal cancer." (PMID 31832017, 2019). "The correlation between high levels of Fbxw11 expression and tumors has been reported in skin tumors and colorectal cancer, among others." (PMID 29555946, 2018).
cervical cancer (4 papers, 2019 to 2023). A primary or metastatic malignant neoplasm involving the cervix. "FBXW11 is also implicated in the proliferation and migration/invasion of cervical cancer cells as a target of microRNA." (PMID 34642302, 2021). "Previous studies have shown that FBXW11 exerts an oncogenic role by promoting tumor cell growth and migration (e.g., in leukemia and cervical cancer)." (PMID 34642302, 2021).
lymphocytic leukemia (4 papers, 2018 to 2024). "Furthermore, the high-level expression of three variants of the Fbxw11 transcript in the lymphocytic leukemia cell line L1210 accelerated proliferation in vitro and promoted tumor formation in vivo." (PMID 29555946, 2018). "In the present study, we examined the expression of Fbxw11 in leukemia samples and explored the role of Fbxw11 in lymphocytic leukemia cells using in vitro and in vivo experiments." (PMID 29555946, 2018). "High levels of Fbxw11 expression stimulate the proliferation of L1210 lymphocytic leukemia cells in vitro and promote tumor formation in vivo by regulating the cell cycle." (PMID 29555946, 2018). "The high level of Fbxw11 expression in L1210 lymphocytic leukemia cells stimulated cell proliferation in vitro and tumor formation in vivo." (PMID 29555946, 2018). "Our results reveal the role of Fbxw11 in lymphocytic leukemia cells and imply that Fbxw11 may serve as a potential molecular target for the treatment of lymphocytic leukemia." (PMID 29555946, 2018). "This work reveals the role of Fbxw11 in the proliferation of lymphocytic leukemia cells and implies that Fbxw11 may serve as a potential molecular target for the treatment of lymphocytic leukemia." (PMID 29555946, 2018). "In this study, Fbxw11 expression was aberrantly upregulated in patients with lymphocytic leukemia." (PMID 29555946, 2018). "Moreover, FBXW11 promotes the activation of the NF-κB and β-catenin/TCF signaling pathways, inducing cell cycle progression and tumor formation in lymphocytic leukemia." (PMID 31832017, 2019). "Moreover, Fbxw11-mediated concomitant activation of the NF-κB and β-catenin/T-cell factor (TCF) signaling pathways contributed to increased proliferation in lymphocytic leukemia cells." (PMID 29555946, 2018).
leukemia (3 papers, 2018 to 2022). A malignant (clonal) hematologic disorder, involving hematopoietic stem cells and characterized by the presence of primitive or atypical myeloid or lymphoid cells in the bone marrow and the blood. "Our results not only elucidate the significance of the Fbxw11-associated UPS in the progression of ALL but also provide new insights for leukemia research and clinical therapy." (PMID 29555946, 2018). "However, the role of Fbxw11 in the development of leukemia and the underlying mechanisms remain largely unknown." (PMID 29555946, 2018). "In our previous studies, Fbxw11 is upregulated in acute lymphocytic leukemia, and high level of Fbxw11 expression promotes the proliferation of leukemia cells." (PMID 35690796, 2022). "DBA/2J mice were subcutaneously injected with 1 × 106 L1210-control, L1210-Fbxw11a, L1210-Fbxw11c, and L1210-Fbxw11d cells (n = 5/group) to further examine the effects of Fbxw11 on the proliferation of leukemia cells in vivo." (PMID 29555946, 2018). "Interactive hierarchical tree showed the difference of Fbxw11 expression among different types of leukemia." (PMID 29555946, 2018). "Cell proliferation, apoptosis, and migration were investigated to assess the effects of Fbxw11 on leukemia cells in vitro." (PMID 29555946, 2018). "However, little is known about the effects of Fbxw11 on leukemia cells." (PMID 29555946, 2018). "However, the role of Fbxw11 in leukemia development remains largely unknown." (PMID 29555946, 2018). "Based on the analysis of the GSE13159 dataset from Microarray Innovations in Leukemia (MILE), Fbxw11 was expressed at significantly higher levels in the ALL or chronic lymphocytic leukemia (CLL) group than the healthy BM group." (PMID 29555946, 2018).
breast carcinoma (2 papers, 2021 to 2024). "Elevated expression of FBXW11 has become a common trend in various human cancers, such as hematopoietic malignancy, prostate carcinoma, and breast cancer." (PMID 34642302, 2021).
lung cancer (2 papers, 2023 to 2025). A malignant neoplasm involving the lung. "On the contrary, FBXW11 suppression promotes tumour proliferation in non‐small cell lung cancer cells." (PMID 37199076, 2023).
melanoma (2 papers, 2019 to 2023). A malignant, usually aggressive tumor composed of atypical, neoplastic melanocytes. "However, by using parental and RUNT KO melanoma cells, both expressing similar FBXW11 and beta‐catenin levels, we observed that RUNT domain is able to prevent proteasome degradation of RUNX2 regardless of the expression of FBXW11." (PMID 37199076, 2023). "To evaluate whether FBXW11 has a direct role in the degradation of RUNX2 by the proteasome system, we used a melanoma cellular model in which RUNX2 differs only in the RUNT domain." (PMID 37199076, 2023).
osteosarcoma (2 papers, 2023 to 2025). A usually aggressive malignant bone-forming mesenchymal neoplasm, predominantly affecting adolescents and young adults. "In particular, we explored the FBXW11 expression in normal osteogenic cells as well as in cells of cleidocranial dysplasia (CCD) patients or osteosarcoma cells." (PMID 37199076, 2023). "Accordingly, miR‐221 was higher in osteosarcoma cells compared to HOB, suggesting that epigenetic alterations play an important role in osteosarcoma also by modulating FBXW11 expression." (PMID 37199076, 2023). "We analysed the expression levels of FBXW11 in normal osteoblasts and osteosarcoma cells expressing higher RUNX2 levels." (PMID 37199076, 2023). "Moreover, miR-221 inhibits the Wnt signaling pathway by directly targeting FBXW11, thereby facilitating osteosarcoma cell proliferation and suppressing apoptosis." (PMID 40747341, 2025). "However, the FBXW11 expression modulation between osteosarcoma and normal osteoblast has been poorly investigated." (PMID 37199076, 2023). "Conversely, in osteosarcoma cells, the reduction of FBXW11 protein levels increases beta‐catenin." (PMID 37199076, 2023). "In addition, FBXW11 is post‐transcriptionally regulated in osteosarcoma cells leading to increased levels of beta‐catenin." (PMID 37199076, 2023). "However, by performing gene expression analyses we observed that FBXW11 was overexpressed in osteosarcoma cells compared to HOB." (PMID 37199076, 2023). "Therefore, all these results suggest that FBXW11 exerts its function specifically in the cellular context and, relatively to osteosarcoma, this protein can be considered an important marker for evaluating disease progression." (PMID 37199076, 2023). "We observed lower FBXW11 protein levels in MG63 and U2OS osteosarcoma cells compared to normal osteoblasts (HOB)." (PMID 37199076, 2023). "Our data showed lower FBXW11 protein levels in MG63 and U2OS osteosarcoma cells compared to normal osteoblasts." (PMID 37199076, 2023). "However, when we analysed FBXW11 gene expression levels in the U2OS and MG63 osteosarcoma cell lines we observed higher levels than in normal osteoblasts." (PMID 37199076, 2023). "Since beta‐catenin promotes tumour formation and progression, reduced FBXW11 levels in osteosarcoma may be considered a negative prognostic factor." (PMID 37199076, 2023).
ovarian carcinoma (2 papers, 2024 to 2025). A malignant neoplasm originating from the surface ovarian epithelium. "For the first time, we demonstrated that FBXW11 functions by modulating the S100A11-mediated DNA damage repair pathway to enhance ovarian cancer cells' susceptibility to PARPis." (PMID 40747341, 2025). "In summary, our study confirms that FBXW11 promotes the susceptibility of ovarian cancer cells to PARPi via affecting S100A11-mediated DNA damage repair." (PMID 40747341, 2025). "In this study, RNA sequencing (RNA-seq) showed that FBXW11 expression was raised in ovarian cancer cells that had been treated with PARPi." (PMID 40747341, 2025). "The findings indicated that FBXW11 overexpression expedited the degradation of S100A11 in ovarian cancer cells." (PMID 40747341, 2025). "Experiments in the xenograft models further validated that FBXW11 overexpression promoted the therapeutic effect of PARPi in ovarian cancer in vivo." (PMID 40747341, 2025). "The overexpression of FBXW11 markedly enhanced the sensitivity of ovarian cancer cells to PARPi, while the knockdown of FBXW11 facilitated resistance to PARP inhibitors." (PMID 40747341, 2025). "The Cancer Genome Atlas (TCGA) data indicated that FBXW11 is present at low levels in multiple cancers of human tissues, consisting of ovarian cancer." (PMID 40747341, 2025). "Precise upregulation of FBXW11 has the potential to enhance the clinical response of ovarian cancer to PARPi." (PMID 40747341, 2025). "The combination of FBXW11 overexpression or S100A11 inhibition with PARPi might have great potential in the medical therapy of ovarian cancer." (PMID 40747341, 2025). "To clarify whether the upregulation of FBXW11 contributes to olaparib-mediated killing or enhances olaparib tolerance in ovarian cancer cells, we silenced the expression of FBXW11 in these three cell lines using siRNA." (PMID 40747341, 2025). "We initially examined FBXW11 expression in both ovarian cancer tissue and normal ovarian tissue." (PMID 40747341, 2025). "We then determined the half maximal inhibitory concentration (IC50) value by CCK-8 assay, and we found that after knockdown of FBXW11, the IC50 value of olaparib was increased compared with the control group in all three ovarian cancer cell lines." (PMID 40747341, 2025). "Additionally, FBXW11 facilitates the degradation of S100A11 via ubiquitination, thereby increasing the sensitivity of ovarian cancer cells to PARPi." (PMID 40747341, 2025). "However, there are no relevant reports on FBXW11 expression in ovarian cancer or its function in ovarian cancer treatment." (PMID 40747341, 2025).
pancreatic cancer (2 papers, 2023). "miR-10a and miR-182 directly bind to the 3′-UTR of BTRC, and FBXW11 degrades their mRNAs in human aortic endothelial cells and in pancreatic cancer cells, respectively." (PMID 37686524, 2023).
skin tumors (2 papers, 2018 to 2021). "Furthermore, Fbxw11 is overexpressed in mouse skin tumors and accelerates tumor progression by activating the NF-κB signaling pathway." (PMID 29555946, 2018).
acute leukemia (1 paper, 2018). A clonal (malignant) hematopoietic disorder with an acute onset, affecting the bone marrow and the peripheral blood. "Fbxw11 expression in patients with acute leukemia (AL) was investigated using real-time PCR." (PMID 29555946, 2018).
brain tumors (1 paper, 2024). "On the other hand, FBXW11 protein levels were significantly lower in brain tumors and uterine tumors than in the corresponding normal control tissues." (PMID 38672111, 2024).
breast tumors (1 paper, 2022). "Higher FBXW11 expression is a factor that promotes cell transformation, and it has been shown that in mammary tissues of transgenic mice with negative FBXW11 expression, the development of breast tumors is reduced." (PMID 36476410, 2022).
colon cancer (1 paper, 2014). "We note that mutations in beta-catenin, FBXW11’s substrate, have also been observed in colon cancer, where they affect Ser and Thr residues that are essential for the phosphorylation-dependent degradation of beta-catenin." (PMID 24362839, 2014).
colorectal tumor (1 paper, 2021). "FBXW11 was overexpressed in colorectal tumor tissues and its overexpression was associated with a poor prognosis of CRC patients." (PMID 34642302, 2021). "In the present study, FBXW11 was highly expressed in colorectal tumor tissues and its overexpression was associated with a poor prognosis of CRC patients." (PMID 34642302, 2021). "The upregulation of FBXW11 significantly increased the viability, promoted the colony formation capacity, and inhibited the apoptosis of colorectal tumor cells, whereas FBXW11 deficiency suppressed cell growth and proliferation." (PMID 34642302, 2021). "Next, we examined whether HIC1 was implicated in FBXW11-mediated colorectal tumor growth." (PMID 34642302, 2021). "The xenograft models further confirmed that the downregulation of FBXW11 impeded colorectal tumor growth and inhibited liver metastasis in vivo." (PMID 34642302, 2021). "The upregulation of FBXW11 not only promoted cell proliferation, invasion, and migration, but also contributed to maintaining stem-cell features in colorectal tumor cells." (PMID 34642302, 2021). "To investigate the effects of FBXW11 expression on colorectal tumor growth, we first measured the level of FBXW11 in different CRC cells compared with normal colon mucosal epithelial cells NCM460." (PMID 34642302, 2021). "The mouse xenograft models of CRC confirmed that FBXW11 knockdown impeded colorectal tumor growth and liver metastasis in vivo." (PMID 34642302, 2021). "The result showed that FBXW11 was significantly upregulated in colorectal tumors." (PMID 34642302, 2021). "Similarly, we found that the upregulation of FBXW11 increased cell viability and promoted invasion and migration of colorectal tumor cells, whereas FBXW11 depletion suppressed cell proliferation and mobility." (PMID 34642302, 2021). "The immunohistochemistry staining revealed that the expressions of FBXW11 and SIRT1 in human colorectal tumors were positively correlated." (PMID 34642302, 2021). "To explore whether FBXW11 was involved in the progression of CRC, we first analyzed the mRNA expression of FBXW11 in 145 pairs of colorectal tumor tissues and paired non-tumorous tissues." (PMID 34642302, 2021).
hepatocellular carcinoma (1 paper, 2021). A malignant tumor that arises from hepatocytes. "FBXW11 and its paralog FBXW1 have been shown to specifically interact with and promote the ubiquitination of Lipin1, a multifunctional phosphatidate phosphatase, in hepatocellular carcinoma cells, thereby promoting hepatic lipogenesis." (PMID 34642302, 2021).